RN7SKP102 (RN7SK pseudogene 102)
Gene: Miscellaneous RNA gene on chromosome 2 (123,869,256 to 123,869,570, reverse strand). Ensembl gene ENSG00000223118.
Homologues: Orthologues: chimpanzee 7SK (97% identical), mouse Gm55378 (57% identical). Paralogues in human: 7SK (76% identical), RN7SKP255 (76% identical), RN7SKP180 (74% identical), RN7SKP71 (74% identical), RN7SKP173 (74% identical), RN7SKP203 (74% identical), RN7SKP294 (74% identical), RN7SKP133 (73% identical), RN7SKP176 (73% identical), RN7SKP204 (73% identical), RN7SKP78 (73% identical), RN7SKP189 (73% identical), and 284 more.